TH (tyrosine hydroxylase)
Diseases named in the same sentence as TH in open-access papers (continued):
Sharing a sentence is not in itself a finding about the gene and the disease.
movement disorder (14 papers, 2014 to 2025). Neurological conditions resulting in abnormal voluntary or involuntary movement, which may impact the speed, fluency, quality and ease of movement. "Furthermore, TH signals were instrumental in characterizing the basal ganglia (BG), a group of subcortical nuclei implicated in motor control and movement disorders." (PMID 39630862, 2024). "We also introduce the relation between the loss of TH protein and the propagation of α-synuclein, which is a well-known protein in PD pathology, to clarify the mechanism underlying the reduction of nigrostriatal dopamine function and the loss of TH protein in these movement disorders." (PMID 32471089, 2020). "With respect to the possible mechanism of FIP, in addition to the more D2 receptor blocker, loss of tyrosine hydroxylase in the monoaminergic presynaptic neuron may lead to dopamine deletion and cause movement disorders." (PMID 31920674, 2019). "In this study, we for the first time show that Nedd4-2 knockdown ameliorates the movement disorder in PD model and increases the percentage of TH-positive neurons in the SN and TH density in striatum." (PMID 28151476, 2017). "The reduction in TH protein and DA levels by different mechanisms might induce the propagation of the movement disorders during the process of dopaminergic cell death." (PMID 33902532, 2021). "Notably, we demonstrate for the first time that Nedd4-2 knockdown ameliorates the movement disorder in PD mice and increases tyrosine hydroxylase (TH) expression in PD mice." (PMID 28151476, 2017). "Thus, the tyrosine hydroxylase level is elevated and dopamine is released, leading to the movement disorder." (PMID 25562024, 2014).
neurological disorders (13 papers, 2010 to 2025). "Since alteration in TH activity and DA synthesis/signaling has been found to be associated with PD and other neurological disorders, modulation of TH activity or DA signaling has been proposed as a potential therapeutic strategy for the treatment of PD." (PMID 34732185, 2021). "TH protein is among the first binding partners associated with several neurological diseases." (PMID 33767733, 2021). "Abnormal expression of TH is related to the occurrence of a variety of neurological diseases." (PMID 32878312, 2020). "The DPSC-derived iPSCs have ability to differentiate into β-III tubulin neuron-like cells and tyrosine hydroxylase-positive dopaminergic neuron-like cells and may become another DPSC-related cell sources for the treatment of nervous system diseases in the future." (PMID 29853908, 2018). "Treatment that increase Ser31 or Ser40 phosphorylation but not the others increase TH activity and catecholamine biosynthesis, and ERK-mediated phosphorylation of Ser31 play a role in dopaminergic related neurological disease." (PMID 20074377, 2010).
cancer (11 papers, 2017 to 2024). A tumor composed of atypical neoplastic, often pleomorphic cells that invade other tissues. "The density of sympathetic TH-positive fibers and its proportion to all fibers was lower in cancer than in the periphery and BP samples." (PMID 34277455, 2021). "The antitumor drug CPT was conjugated to the new TH analogs, and its pH-dependent cytotoxicity to cancer cells was compared." (PMID 28603674, 2017). "Although data from cancer models are limited, in hyperglycemic conditions, the spleens of diabetic patients and mice harbor increased numbers of tyrosine hydroxylase (TH)-expressing leukocytes that produce catecholamines, and GMPs that are actively proliferating." (PMID 32582203, 2020). "In addition, these new TH analogs were linked to the antitumor drug camptothecin (CPT), while butyl-TH modified conjugate presented a remarkably stronger pH-dependent cytotoxicity to cancer cells than TH and the other conjugates." (PMID 28603674, 2017). "The decreased intracellular cAMP would cause inactivation of PKA and its downstream proteins, such as PDE, BAD, HSL, PHK, TH, NAFT, and Filamin, in turn affect the metabolic energy, lipolysis, glycolysis, tyrosine metabolism, and cytoskeletol regulation in cancer cells." (PMID 28117370, 2017).
psychiatric disorder (7 papers, 2011 to 2025). A disorder characterized by behavioral and/or psychological abnormalities, often accompanied by physical symptoms. "The tyrosine hydroxylase takes in a key role in the synthesis of catecholamines, that is, dopamine, adrenaline, and noradrenaline, which have also been linked with stress‐related psychiatric disorders and resilience." (PMID 33052028, 2020).
genetic disorder (4 papers, 2015 to 2024). "Consistent with this is the accumulation of a wide spectrum of ubiquitinated protein aggregates in brains of PD patients, such as tyrosine hydroxylase (TH), synphilin-1, α-synuclein, and phosphorylated tau, which constitutes the most common form of the idiopathic and genetic disease." (PMID 37644186, 2024).
TH also shares sentences with these, for which no sentence is quoted: asthma (5 papers); bipolar disorder (4); autism spectrum disorder (3); Bradykinesia (2); Brain atrophy (2); cardiovascular disease (2); Encephalopathy (2); mental disorder (2); mood disorder (2); multiple sclerosis (2); multiple system atrophy (2); neurotoxicity (2); opiate dependence (2); absence seizures (1); acromegaly (1); Addison's disease (1); adjustment disorder (1); Adult onset (1); age-related macular degeneration (1); alcoholic hepatitis (1); alopecia (1); amyotrophic lateral sclerosis (1); and motor delay (1); aphakia (1); asphyxia (1); astrocytoma (1); Atrophy (1); attention deficit-hyperactivity disorder (1); autoimmune disease (1); brain diseases (1).
A further 92 diseases each share a sentence with TH in 1 paper.